AKT1 (AKT serine/threonine kinase 1)
Diseases named in the same sentence as AKT1 in open-access papers (continued):
Sharing a sentence is not in itself a finding about the gene and the disease.
thymoma (18 papers, 2016 to 2025). A neoplasm arising from the epithelial cells of the thymus. "Based on network pharmacology, we found that AKT1 was the core target of dexamethasone in the treatment of thymoma-associated MG." (PMID 37498332, 2024). "We found that AKT1 was enriched in the MEpurple module and was highly associated with type B3 thymomas." (PMID 37498332, 2024). "The expressions of AKT1 and its downstream molecule mTOR in the thymoma microenvironment of thymoma-associated MG patients who did not receive dexamethasone before operation were higher than those in the group receiving dexamethasone before operation." (PMID 37498332, 2024). "We have also successfully verified that dexamethasone may act on thymoma-associated MG through the AKT1-mTOR pathway in clinical patients, which was rarely studied before." (PMID 37498332, 2024). "Thus, we continued to verify the positive effect of dexamethasone on thymoma-associated MG focusing on the AKT1 and its downstream factor mTOR." (PMID 37498332, 2024). "Statistics showed that the expressions of AKT1 and mTOR in the thymoma TME of the dexamethasone-treated group were lower than those of the non-dexamethasone-treated group." (PMID 37498332, 2024). "The thymoma tissues of the enrolled patients were selected to verify the expression of AKT1 and mTOR." (PMID 37498332, 2024). "Our research screened out the core target genes AKT1, MMP9, STAT3, SRC, and EGFR of thymoma-associated M, and carried out molecular docking verification." (PMID 37498332, 2024). "The results showed that the level of AKT1 and mTOR protein in all 5 thymoma patients who received DXMS treatment was lower than that in the non-DXMS group, while the level of apoptosis protein, cleaved caspase-3, showed the opposite trend." (PMID 37498332, 2024). "We did not detect mutations in PIK3CA and AKT1 in type A and B3 thymomas or thymic carcinomas." (PMID 27844328, 2017). "Our results also confirmed that the expression level of AKT1 and mTOR were decreased and the expression level of the apoptosis-related protein, cleaved-caspase-3, was increased in the TME of thymoma patients using DXMS, which also suggested that DXMS promoted apoptosis of thymoma cells." (PMID 37498332, 2024). "Our study showed that in the thymoma TME, the expressions of AKT1 and mTOR in the non-dexamethasone treatment group were higher than those in the dexamethasone treatment group." (PMID 37498332, 2024).
gastric tumor (17 papers, 2010 to 2023). "On the other hand, Cbx7 acts as an oncogene in gastric tumors by suppressing p16/CDKN2A and supporting AKT1 signaling pathway." (PMID 36361869, 2022). "In these gastric tumour samples, there was a non-significant correlation between AKT1 and CDH1 expression (correlation 0.081, p = 0.1)." (PMID 31540244, 2019). "Gene expression analysis of gastric tumour samples from The Cancer Genome Atlas (TCGA) stomach adenocarcinoma (STAD) cohort revealed that the expression of the AKT3 isoform (but not AKT1 or AKT2) is inversely correlated to the expression of CDH1 in gastric tumours." (PMID 35406381, 2022).
metastatic melanoma (17 papers, 2015 to 2025). A melanoma that has spread from its primary site to another anatomic site. "LINC00518 and LINC00520 were each found to be independent risk factors for metastatic melanoma patient survival and the network motif UCA1/hsa-miR-125b-1/AKT1 has an 88% chance of correctly identifying a TCGA sample as metastatic melanoma." (PMID 35008286, 2021). "The results suggested a prognostic value of motif 3 (UCA1/AKT1/hsa-miR-125b-1) for discriminating metastatic and non-metastatic melanoma phenotypes with a high prediction accuracy (ACC = 0.88)." (PMID 32703153, 2020). "Relative to AKT1, AKT3 was upregulated and AKT2 downregulated in all the VGP and metastatic melanoma cell lines tested." (PMID 25595898, 2015). "In metastatic melanomas, it has been reported in the past that the selective activation of Akt3, but not Akt1/2, increases the survival rate of tumorigenic cells and tumor development in 40–60% of non-familial melanomas." (PMID 32962144, 2020).
rhabdomyosarcoma (17 papers, 2007 to 2025). A rare aggressive malignant mesenchymal neoplasm arising from skeletal muscle. "This study identifies c-Myc/AKT1/TBX3 as an important axis that could be targeted for the treatment of rhabdomyosarcoma." (PMID 32098189, 2020).
ulcerative colitis (17 papers, 2020 to 2025). An inflammatory bowel disease involving the mucosal surface of the large intestine and rectum. "Lucidenic acid A emerged as the most promising compound, demonstrating exceptional binding to SRC (−9.1 kcal/mol), EGFR (−8.3 kcal/mol), and AKT1 (−8.8 kcal/mol), suggesting a multi-target therapeutic approach advantageous for treating the complex pathophysiology of ulcerative colitis." (PMID 41465478, 2025). "Molecular docking studies were performed to evaluate the binding affinity and interaction profiles of ten bioactive compounds from BRLE against the four key protein targets (EGFR, SRC, STAT3, and AKT1) identified through network pharmacology analysis for ulcerative colitis treatment." (PMID 41465478, 2025). "The molecular docking analysis revealed promising binding affinities of ten BRLE bioactive compounds against four key ulcerative colitis-related targets (EGFR, SRC, STAT3, and AKT1), with binding scores ranging from −6.5 to −9.1 kcal/mol." (PMID 41465478, 2025). "JUN, Akt1, and MAPK1 were identified as the “hub targets” involved in the effects of Modified Sanmiaosan on ulcerative colitis." (PMID 35966251, 2022).
injury (16 papers, 2018 to 2025). Damage inflicted on the body as the direct or indirect result of an external force, with or without disruption of structural continuity. "In summary, the results presented here showed that AKT1-modified BM-MSCs had a survival advantage and an enhanced immunomodulatory function compared to unmodified BM-MSCs, leading to better amelioration of ConA-induced liver injury." (PMID 31889917, 2019).
pulmonary hypertension (16 papers, 2014 to 2025). Increased pressure within the pulmonary circulation due to lung or heart disorder. "Knockout of AKT1 in mice was also demonstrated to attenuate vascular remodeling and exhibited a protective effect against the development of hypoxia-induced pulmonary hypertension." (PMID 38057829, 2023). "The knockout of the Akt1 gene in mice was also reported to attenuate pulmonary vascular remodeling and to reduce the wall thickness of the pulmonary artery, which reflects its protective effect against the disease course of hypoxia-induced pulmonary hypertension." (PMID 35740436, 2022).
Arthritis (15 papers, 2019 to 2025). Inflammation of a joint. "The Akt1/NF-κB axis is involved in the inflammatory injury process of collagen-induced arthritis in mice." (PMID 35287352, 2022). "For example, circRNA_09505 promoted polarization of M1 phenotype macrophages through sponging miR-6089 to maintain activation of the AKT1/nuclear factor (NF)-κB signaling pathway in a gene-induced arthritis mouse model." (PMID 36402996, 2022). "In the present study, PTEN mRNA expression was decreased in RA patients, while the PTEN expression was decreased in the synovial tissue in the arthritis model, and PI3K and Akt1 protein expressions were increased." (PMID 36330380, 2022). "Adiponectin enhances B-cell proliferation and differentiation via activation of Akt1/STAT3 and exacerbates collagen-induced arthritis." (PMID 35628866, 2022).
cognitive decline (15 papers, 2010 to 2025). "Hyperphosphorylation of AKT1 in the brain has been associated with increased amyloid burden, tau tangle density, and cognitive decline in AD patients." (PMID 40823947, 2025). "Studies have shown that AKT1 is associated with cognitive decline and plays a role in emotional memory learning in the amygdala, which is the main area of emotional perception, whereas amygdala dysfunction causes ASD core social problems." (PMID 35178102, 2022). "Here, we found that a substantial decrease of IEG expression during memory challenge and molecularly, an increase of markers of neurodegeneration and a decrease of expression of components of the mTOR/Akt1 signaling cascade are associated with the cognitive decline in aging Tsc2+/− animals." (PMID 39192595, 2024). "Taken together, these findings suggest that brain insulin signaling is associated with late-life cognitive decline and that AKT1 phosphorylation may be preferentially associated with a decline in memory, whereas IRS1 phosphorylation may be preferentially associated with perceptual speed." (PMID 38029396, 2024). "We found that a higher level of AKT1 phosphorylation (pT308AKT1/total AKT1) was associated with both a lower level of global cognitive function proximate to death (main effect of the predictor) and a faster rate of cognitive decline (interaction of the predictor with time)." (PMID 38029396, 2024). "Furthermore, FGF21’s neuroprotective benefits were associated with a rapid increase in phosphorylation in Akt1 and other signaling pathways, which may aid in amelioratory cognitive decline." (PMID 32267096, 2020). "The antipsychotic chlorpromazine restores the REV-ERBα level by normalizing DNA methylation through the inhibition of PI3K/AKT1 pathway, and prevents the overexcitation of innate immune cells and cognitive decline in KI/+ mice." (PMID 35418126, 2022). "Future research is needed to confirm our findings and investigate whether normalizing brain insulin signaling along the AKT1 pathway can slow down the late-life cognitive decline and the development of AD." (PMID 38029396, 2024).
invasive breast carcinoma (15 papers, 2005 to 2024). A carcinoma that infiltrates the breast parenchyma. "Finally, we found, in a univariate analysis of 1105 samples of breast invasive cancer from TCGA, that patients that carry mutations that increase abundance of AKT1 mRNA level have a better outcome than patients with mutations at the level of AKT2, who have shorter overall survival." (PMID 28287129, 2017). "For invasive breast cancer the balance between Akt1 and Akt2 in combination with either high Twist or low miR200 and E-cadherin expression seems to be relevant for the development of an EMT-like phenotype." (PMID 38291468, 2024). "Increased expression of EZH2 associates with decreased nuclear expression of phospho-BRCA1 (Ser1423) and upregulation of phospho-Akt-1 (Ser473) in ~ 40% of invasive breast carcinomas." (PMID 33330580, 2020). "In this study, we evaluate subcellular Skp2 expression in invasive breast carcinoma by immunohistochemistry to analyze the relationship between p-Akt1 and cytoplasmic Skp2 expression, and correlate the presence of cytoplasmic Skp2 with patient survival." (PMID 23300741, 2012). "For invasive breast carcinoma patients with high cytoplasmic Skp2 and low p-Akt1 level, Skp2 inhibitors may represent a potential therapeutic strategy." (PMID 23300741, 2012). "Results demonstrate that combined cytoplasmic Skp2 and p-Akt1 expression may be prognostic for patients with invasive breast carcinomas, and cytoplasmic Skp2 may serve as a potential therapeutic target." (PMID 23300741, 2012). "Elevated cytoplasmic Skp2 expression with low p-Akt1 expression was associated with poor disease-free and overall survival (DFS and OS), and Cox regression models demonstrated that cytoplasmic Skp2 expression was an independent prognostic marker for invasive breast carcinomas." (PMID 23300741, 2012). "We extend these results to show that a significant correlation exists between cytoplasmic Skp2 and p-Akt1 expression in patients, and suggests that increased cytoplasmic Skp2 expression may be at least partly due to Akt1 activation in invasive breast carcinomas." (PMID 23300741, 2012). "We verified the correlations among mPRα, p-Akt1 S473 and BCRP in primary breast invasive cancer by IHC." (PMID 33912444, 2021). "Expression of mPRα, p-Akt1, and BCRP in invasive breast cancer." (PMID 33912444, 2021). "Similar to invasive breast cancers, no coexistent PIK3CA mutations were detected in tumours with AKT1 mutations consistent with their role within the same pathway." (PMID 26078038, 2015). "Furthermore, we evaluated The Cancer Genome Atlas (TCGA) dataset for invasive breast carcinomas and found that increased AKT2 but not AKT1 mRNA levels correlated with a worse clinical outcome." (PMID 28287129, 2017).
kidney cancer (15 papers, 2014 to 2024). Primary or metastatic malignant neoplasm involving the kidney. "We analyzed the high/low expression of AKT1 and clinicopathological characteristics of kidney cancer." (PMID 36286049, 2022). "The pathology of 58 kidney cancer patients was constructed to analyze the relationship between the expression level of AKT1 through immunohistochemical staining and their clinicopathological data." (PMID 36286049, 2022). "However, the correlation between AKT1 expression and kidney cancer grade and stage is still controversial." (PMID 36286049, 2022).
non-alcoholic fatty liver disease (15 papers, 2013 to 2026). "Other pathways include pathways in cancer (IL6 and AKT1), non-alcoholic fatty liver disease (AKT1 and IL1B), and the CAMP signaling pathway (AKT1)." (PMID 41601963, 2026).
vascular malformation (15 papers, 2020 to 2025). A non-neoplastic disorder that is the result of defects of vascular morphogenesis. "Given the numerous variants identified in PI3K pathway components (PIK3CA, AKT1, and PTEN) in overgrowth, PIK3R1 is an excellent candidate gene for vascular malformations and overgrowth." (PMID 34040190, 2021). "Upon inducing Cre induction, we observed that AKT1 deletion in capillaries and veins led to a moderate extension of lifespan (median survival of 80 days) and only delayed the occurrence of vascular malformations as MRI performed at 6 weeks still revealed diffused venous malformations." (PMID 38880808, 2024). "And recurrently mutated genes were identified in several vascular malformations as well including TEK/TIE2 mainly in venous malformations, GNA11/14 mainly in vascular tumors, KRAS/NRAS/RASA1/HRAS mainly in AVMs, GNAQ, IDH1/2, AKT1, PTEN and PIK3CA." (PMID 34736485, 2021). "They demonstrated in a mouse experimental model that sustained AKT1 activation and overexpression in MS1 endothelial cells injected subcutaneously induced vascular malformations with proliferating hemangiomas by stimulating endothelial cell proliferation independently of the Ras-mediated pathway." (PMID 35740845, 2022).
chronic kidney disease (14 papers, 2019 to 2025). Impairment of the renal function secondary to chronic kidney damage persisting for three or more months. "AKT1 (also known as mitochondrial protein kinase B) indirectly prevents the development of glomerulosclerosis and subsequent chronic kidney disease." (PMID 36389115, 2022).
diabetic retinopathy (14 papers, 2008 to 2025). "The effect of Akt1 deficiency on vascular leakage was confirmed by establishing a diabetic retinopathy model by injecting Akt1∆SMC mice with STZ." (PMID 35931736, 2022). "In summary, the results of the present study demonstrate that Mingmu Dihuang pill may be effective for the clinical treatment of diabetic retinopathy through active ingredients luteolin, acacetin, naringenin, and alisol B via AKT1, SRC, and VEGFA in AGE-RAGE, PI3K-AKT, and Rap1 signaling pathways." (PMID 36467890, 2022). "Molecular docking confirmed a good binding affinity of active ingredients of MMDHP, including luteolin, acacetin, naringenin, and alisol B, with AKT1, SRC, and VEGFA as the three key targets of diabetic retinopathy." (PMID 36467890, 2022). "Molecular docking confirmed a good binding affinity of active ingredients of Mingmu Dihuang pill, including luteolin, acacetin, naringenin, and alisol B, with AKT1, SRC, and VEGFA, three hub targets of diabetic retinopathy." (PMID 36467890, 2022). "MMDHP may be effective for the treatment of diabetic retinopathy through active ingredients luteolin, acacetin, naringenin, and alisol B via AKT1, SRC, and VEGFA in AGE-RAGE, PI3K-AKT, and Rap1 signaling pathways." (PMID 36467890, 2022). "AKT1, SRC, and VEGFA were found to have the binding energy of < −5 kcal/mol with all key targets of diabetic retinopathy, suggesting the good binding energy towards the key targets of diabetic retinopathy." (PMID 36467890, 2022). "Consistent with our findings in the RPE of diabetic mice, reciprocal regulation of AKT1 and AKT2 phosphorylation in the RPE was observed in human diabetic retinopathy donor cadaver samples, compared to nondiabetic controls." (PMID 36229454, 2022).
lupus (14 papers, 2012 to 2025). "Dectin3 inhibited the nuclear metastasis of FoxO1 in lupus MDSCs through the Syk-Akt1 signal axis and participated in the development of lupus." (PMID 34480018, 2021). "The phosphorylation of Akt1 and Syk reduced in MDSCs of Dectin3−/− mice with lupus compared with WT mice with lupus." (PMID 34480018, 2021). "Importantly, we demonstrated that AKT1 overexpression exacerbated PANoptosis in glomerular cells, thereby aggravating renal pathology—manifested as enhanced renal inflammation, aggravated lupus-like pathological changes, and increased proteinuria." (PMID 41573714, 2025). "Additionally, Hyp alleviated AKT1 overexpression-aggravated renal inflammation, lupus-like pathological changes, and proteinuria in MRL/lpr mice." (PMID 41573714, 2025).
autism (13 papers, 2015 to 2025). Persistent deficits in social interaction and communication and interaction as well as a markedly restricted repertoire of activity and interest as well as repetitive patterns of behavior. "The main targets of JWYHT on social communication disorders in autism, including MAPK, AKT1, 5HT1B, and IL6, were investigated using network pharmacology and molecular docking technology in this study." (PMID 35178102, 2022). "Third, through network toxicology, single-cell transcriptomics, and animal experimentation, we demonstrate that chronic PM2.5 exposure exacerbates valproic acid-induced autism-like behaviors in murine models, identifying CTNNB1, PTEN, CCR2, AKT1, and mTOR as potential core mediating genes." (PMID 41304474, 2025).
gastric adenocarcinoma (13 papers, 2014 to 2025). "A survey of 225 human tumors for changes involving AKT1 led to the discovery of a 20-fold amplification of this gene in one of the five gastric adenocarcinomas tested." (PMID 25003395, 2014).